FBXO22 (F-box protein 22)
Diseases named in the same sentence as FBXO22 in open-access papers (continued):
Sharing a sentence is not in itself a finding about the gene and the disease.
osteosarcoma (3 papers, 2020 to 2024). A usually aggressive malignant bone-forming mesenchymal neoplasm, predominantly affecting adolescents and young adults. "Knockdown of FBXO22 inhibited the proliferation of osteosarcoma cells, which was abrogated by shFoxO1 transfection." (PMID 39153212, 2024). "We observed that depletion of FBXO22 increased the expression of FoxO1 at the protein level in osteosarcoma cells." (PMID 39153212, 2024). "In the present study, we reported that FBXO22 plays a tumour‐promoting role in osteosarcoma cells via regulating the abundance of the FoxO1 protein." (PMID 39153212, 2024). "To explore the effect of FBXO22 on the proliferation of osteosarcoma cells, we downregulated the expression of FBXO22 in SaOS‐2 and U2OS cells." (PMID 39153212, 2024). "Taken together, these findings indicated that the downregulation of FBXO22 repressed osteosarcoma cell proliferation by targeting the FoxO1 pathway." (PMID 39153212, 2024). "Our in vitro results showed that depletion of FBXO22 reduced the proliferation of osteosarcoma cells." (PMID 39153212, 2024). "EdU assay data suggested that the overexpression of FBXO22 increased the number of EdU‐positive U2OS, SaOS‐2 and MG63 cells, indicating that the upregulation of FBXO22 promoted the proliferation of osteosarcoma cells." (PMID 39153212, 2024). "Taken together, these findings indicated that depletion of FBXO22 inhibited the proliferation of osteosarcoma cells." (PMID 39153212, 2024). "In osteosarcoma cells, Hou and co‐workers reported that the lncRNA small nucleolar RNA host gene 14 (SNHG14) accelerated tumour progression by targeting miR‐433‐3p and FBXO22 in osteosarcoma." (PMID 39153212, 2024). "A CCK‐8 assay was conducted to detect the proliferation of osteosarcoma cells after FBXO22 downregulation." (PMID 39153212, 2024). "Our findings provide evidence for a novel mechanism by which FBXO22 promotes the degradation of the FoxO1 tumour suppressor in osteosarcoma in part." (PMID 39153212, 2024). "Taken together, these findings indicated that depletion of FBXO22 suppressed the migratory and invasive ability of osteosarcoma cells." (PMID 39153212, 2024). "Transwell migration assays revealed that upregulation of FBXO22 enhanced the migratory ability of osteosarcoma cells." (PMID 39153212, 2024). "For example, miR-433-3p inhibited cell proliferation and metastasis, but contributed to cell apoptosis by binding to F-box protein 22 (FBXO22) in osteosarcoma and through interacting with CREB in glioma." (PMID 33832516, 2021). "Small nucleolus RNA host gene 14 (SNHG14), one long noncoding RNA, was reported to act as a competing endogenous RNA (ceRNA) to decoy miR-433-3p and subsequently increase FBXO22 expression in osteosarcoma cells." (PMID 32793396, 2020). "Token together, SNHG14 enhanced osteosarcoma progression through modulation of miR-433-3p/FBXO22 pathway." (PMID 32793396, 2020). "Determining the correlation between FBXO22 and FoxO1 in osteosarcoma tissues is critical." (PMID 39153212, 2024). "However, the functions and detailed molecular mechanisms of FBXO22 in osteosarcoma tumorigenesis and progression remain elusive." (PMID 39153212, 2024). "Nevertheless, the function and detailed molecular mechanisms of FBXO22 are elusive in osteosarcoma, and further studies are needed to determine whether FBXO22 might be a potent target for therapy in osteosarcoma patients." (PMID 39153212, 2024). "Next, we upregulated the expression of FBXO22 in osteosarcoma cells via FBXO22 cDNA transfection." (PMID 39153212, 2024). "Moreover, we explored the molecular mechanisms by which FBXO22 mediated oncogenesis and progression in osteosarcoma via Western blotting, immunoprecipitation and ubiquitination." (PMID 39153212, 2024). "Consistently, FBXO22 overexpression reduced FoxO1 protein levels in osteosarcoma cells." (PMID 39153212, 2024). "In addition, Transwell invasion assay data confirmed that increased FBXO22 promoted the invasiveness of osteosarcoma cells." (PMID 39153212, 2024).
osteosarcoma (continued). "Knockdown of FBXO22 inhibited the proliferation and motility of 143B and SaOS‐2 osteosarcoma cells." (PMID 39153212, 2024). "Since immunotherapies are useful for osteosarcoma treatment, targeting FBXO22 could be an ideal approach for treating osteosarcoma." (PMID 39153212, 2024). "To determine whether FoxO1 is the substrate of FBXO22, we performed a Western blotting analysis in osteosarcoma cells after FBXO22 depletion or overexpression." (PMID 39153212, 2024). "We found that FBXO22 depletion inhibited the proliferation, migration and invasion of osteosarcoma cells, whereas FBXO22 overexpression increased the proliferation and motility of osteosarcoma cells." (PMID 39153212, 2024). "Moreover, we explored the molecular mechanisms by which FBXO22 mediated oncogenesis and progression in osteosarcoma." (PMID 39153212, 2024). "To test whether depletion of FBXO22 affected cell motility by regulating FoxO1 in osteosarcoma cells, we performed Transwell migration and invasion assays in U2OS and SaOS‐2 cells after shFBXO22 transfection in combination with shFoxO1 treatment." (PMID 39153212, 2024). "However, the relationships among FBXO22, PD‐1, PD‐L1 and FoxO1 in osteosarcoma should be clarified for future immunotherapy application." (PMID 39153212, 2024). "FBXO22 exhibited oncogenic functions in osteosarcoma cells via a reduction in the FoxO1 protein." (PMID 39153212, 2024). "Mechanistically, FBXO22 promoted the ubiquitination and degradation of FoxO1 in osteosarcoma cells." (PMID 39153212, 2024). "Furthermore, the results of the wound healing assay revealed that overexpression of FBXO22 accelerated the rate of wound closure in osteosarcoma cells." (PMID 39153212, 2024). "Therefore, FBXO22 overexpression promoted the proliferation, migration and invasion of osteosarcoma cells." (PMID 39153212, 2024). "Taken together, our findings provide new insight into FBXO22‐induced osteosarcoma tumorigenesis." (PMID 39153212, 2024). "Furthermore, MG132 treatment blocked FoxO1 accumulation in osteosarcoma cells after cotransfection with Myc‐FBXO22 and Flag‐FoxO1." (PMID 39153212, 2024). "The inhibition of FBXO22 could be a promising strategy for the treatment of osteosarcoma." (PMID 39153212, 2024). "Moreover, the development of inhibitors of FBXO22 for the treatment of osteosarcoma is pivotal." (PMID 39153212, 2024). "However, whether FBXO22 affects the proliferation and motility of osteosarcoma cells by targeting FoxO1 and other proteins, such as p57, PTEN and MMP‐9, is elusive." (PMID 39153212, 2024). "Downregulation of FBXO22 or SNHG14 inhibited proliferation, motility of osteosarcoma cells, but stimulated apoptosis." (PMID 32793396, 2020). "It is unclear whether FBXO22 targets the degradation of p57, PTEN and HDM2 in osteosarcoma, which requires future exploration." (PMID 39153212, 2024).
glioma (2 papers, 2021 to 2024). A benign or malignant brain and spinal cord tumor that arises from glial cells (astrocytes, oligodendrocytes, ependymal cells). "Our study strongly indicates that FBXO22 is a promising diagnostic marker and therapeutic target for glioma patients." (PMID 38519492, 2024). "We found that FBXO22 expression was much higher in high-grade glioma patients (III and IV grades) than in low-grade glioma patients (I and II grades)." (PMID 38519492, 2024). "Taken together, our data strongly indicate that FBXO22 is correlated with glioma progression and poor overall patient survival." (PMID 38519492, 2024). "Next, we analyzed FBXO22 expression in glioma patients by glioma tissue microarray (TMA), which contains 428 glioma samples with clinical information and prognosis." (PMID 38519492, 2024). "In this study, we first found that FBXO22 is positively correlated with glioma grade and poor prognosis of glioma patients." (PMID 38519492, 2024). "In the present study, we demonstrate that FBXO22 is highly expressed in glioma and is positively correlated with worse pathological features and shorter survival of GBM patients." (PMID 38519492, 2024). "And we revealed that ectopic expression of FBXO22 promotes glioma cell proliferation, angiogenesis, and cell migration." (PMID 38519492, 2024). "To explore the function of FBXO22 in glioma progression, we first analyzed FBXO22 expression in the TCGA database and CGGA database." (PMID 38519492, 2024). "Then, we tested FBXO22 expression in our collected normal human brain tissues and human glioma tissues by IHC assays." (PMID 38519492, 2024). "The data showed that high FBXO22 expression was positively correlated with poor prognosis in primary glioma." (PMID 38519492, 2024). "In addition, our data also illustrated that glioma patients with high FBXO22 expression had much shorter survival times than those with low FBXO22 expression." (PMID 38519492, 2024). "Our above results have shown that FBXO22 is highly expressed in glioma patients." (PMID 38519492, 2024). "FBXO22 expression was positively correlated with increasing glioma tumor grade." (PMID 38519492, 2024). "Our study suggests that FBXO22 may be a promising therapeutic target for glioma patients." (PMID 38519492, 2024). "Our results showed that the expression levels of FBXO22, HIF-1α, and VEGFA in high-grade gliomas were much higher than those in low-grade gliomas, while the expression level of VHL in high-grade gliomas was much lower than that in low-grade gliomas." (PMID 38519492, 2024). "The expression of FBXO22, VHL, HIF-1α, and VEGFA was detected by IHC staining using anti-FBXO22, VHL, HIF-1α, and VEGFA antibodies in the tissue sections of glioma patients." (PMID 38519492, 2024). "Finally, we confirmed that there are positive correlations among FBXO22, HIF-1α, and VEGFA expression in glioma patients." (PMID 38519492, 2024). "The IHC assay results revealed that FBXO22 expression was positively correlated with the grade of glioma but not with sex, age, or histological type." (PMID 38519492, 2024). "Finally, we wanted to explore the clinical significance of FBXO22 and VHL functions in glioma." (PMID 38519492, 2024). "In addition, our data confirm that there are positive correlations among FBXO22, HIF-1α, and VEGFA expression, and there is a negative correlation between FBXO22 and VHL protein expression in glioma patients." (PMID 38519492, 2024).
liver cancer (2 papers, 2019 to 2024). An epithelial or non-epithelial malignant neoplasm that arises from the liver. "To investigate the correlation between FBXO22 and p21 in HCC, we analyzed the expression of FBXO22 and p21 by IHC on a tissue microarray containing 110 pairs of liver cancer samples with clinical follow-up information." (PMID 30808376, 2019).
lymph node metastasis (2 papers, 2022 to 2024). "Herein, we report that FBXO22 expression is upregulated in CC tissues and associated with higher histology grade and lymph node metastasis in CC patients." (PMID 36127346, 2022). "In multivariate analysis regarding recurrence-free survival (RFS) in ILC patients, Fbxo22 status was independently predictive of survival as well as lymph node metastasis." (PMID 38180699, 2024).
pancreatic carcinoma (2 papers, 2024 to 2025). "Moreover, LATS2 can impede pancreatic cancer cell proliferation via the Hippo signaling pathway, leading to the elimination of F-box protein 22 (FBXO22)-mediated oncogenic effects." (PMID 39866229, 2025).
renal carcinoma (2 papers, 2024). A carcinoma arising from the epithelium of the renal parenchyma or the renal pelvis. "In addition, reports have also discovered that FBXO22 inhibits human renal cancer metastasis and makes non-small cell lung cancer (NSCLC) cells sensitive to ionizing radiation (IR) and cisplatin." (PMID 38519492, 2024).
Salmonella Infections (2 papers, 2012 to 2017). Infections with bacteria of the genus SALMONELLA. "FBXO22 has not been linked to (viral) infections, other than a role in macrophage NFκB activation during Salmonella infection." (PMID 28977405, 2017).
acute lymphoblastic leukaemia (1 paper, 2024). "FBXO22 targets the degradation of the oncoprotein NSD2 in acute lymphoblastic leukaemia cells." (PMID 39153212, 2024).
B cell lymphoma (1 paper, 2024). "The endogenous regulation of BACH1 protein amount by FBXO22 was further examined by using human B cell line Namalwa cells derived from B cell lymphoma." (PMID 38673728, 2024).
brain tumor (1 paper, 2024). "Correspondingly, IHC analysis of the removed mouse brain tumor sections confirmed the high expression of FBXO22, HIF-1α and VEGFA and low expression of VHL in the U87-FBXO22 group compared with the U87-Vector group." (PMID 38519492, 2024).
cervical (1 paper, 2022). "Collectively, we report the tumor-promoting role of FBXO22 in cervical carcinogenesis." (PMID 36127346, 2022).
Cognitive impairment (1 paper, 2022). Abnormal cognition is characterized by deficits in thinking, reasoning, or remembering. "Downregulation of FBXO22 may improve the cognitive deficits caused by propofol, indicating that the FBXO22-mediated protein degradation process also participates in memory formation." (PMID 36425318, 2022). "This study proposes FBXO22 as a potential new target for the treatment of cognitive impairment." (PMID 36425318, 2022).
epithelial ovarian cancers (1 paper, 2021). "HE and IHC staining indicated that FBXO22 deficiency reduced the growth of epithelial ovarian cancers." (PMID 34950036, 2021). "Our study found that FBXO22 expression increased, and the increase was correlated with clinicopathological factors in patients with epithelial ovarian cancers." (PMID 34950036, 2021). "In conclusion, FBXO22 promotes the growth and metastasis of epithelial ovarian cancers cells via the MMP-2 and MAPK pathways." (PMID 34950036, 2021). "This study aims to explore the biological function of FBXO22 in epithelial ovarian cancers progression and metastasis and its specific regulation mechanism." (PMID 34950036, 2021). "We detected the content of MMP-2 in epithelial ovarian cancers cells with interfered and overexpressed FBXO22." (PMID 34950036, 2021). "The results shown that knockdown of FBXO22 inhibited the growth of epithelial ovarian cancers in vivo." (PMID 34950036, 2021). "To explore the mechanism by which FBXO22 promotes the metastasis of epithelial ovarian cancers cells, we identified some related pathways and proteins." (PMID 34950036, 2021). "Our results first reported the function of FBXO22 in epithelial ovarian cancer and the correlation between FBXO22 and autophagy, suggesting FBXO22 as a novel target of epithelial ovarian cancers assessment and treatment." (PMID 34950036, 2021). "Autophagosomes were observed through electron microscope, and the results confirmed that FBXO22 inhibits the autophagy flux of epithelial ovarian cancers cells." (PMID 34950036, 2021). "Immunohistochemistry analysis of tissue microarray was performed to evaluate the expression of FBXO22 in epithelial ovarian cancers patients." (PMID 34950036, 2021). "We found that FBXO22 expression was significantly increased in epithelial ovarian cancers tissues and was closely correlated with clinical pathological factors." (PMID 34950036, 2021). "In summary, our study is the first to report that FBXO22 promotes growth and metastasis and inhibits autophagy in epithelial ovarian cancers, and these functions depend on the MAPK/ERK pathway." (PMID 34950036, 2021). "By contrast, the function of FBXO22 in epithelial ovarian cancers is unclear." (PMID 34950036, 2021). "Furthermore, we established Ctrl-LV3 (NC) and shFBXO22-LV3 (sh-FBXO22) stable cell lines to verify the function of FBXO22 in the regulation of epithelial ovarian cancers cell in vivo." (PMID 34950036, 2021). "The results revealed that FBXO22 promotes cell proliferation in epithelial ovarian cancers." (PMID 34950036, 2021). "The knockdown of FBXO22 inhibited the growth of epithelial ovarian cancers cells." (PMID 34950036, 2021). "Expression of FBXO22 and clinicopathological factors of ovarian cancer patients." (PMID 34950036, 2021). "However, whether FBXO22 inhibits the apoptosis in epithelial ovarian cancers remains unclear." (PMID 34950036, 2021). "Our study demonstrated the correlation between FBXO22 and MAPK/ERK, which may provide new ideas for the treatment of epithelial ovarian cancer." (PMID 34950036, 2021). "However, the function of FBXO22 in epithelial ovarian cancers has not been reported." (PMID 34950036, 2021). "To investigate the biological function of FBXO22 in epithelial ovarian cancers cell proliferation, we transfected HO8910 and OVCAR3 cells with negative control siRNA (NC) and siRNAs targeting FBXO22 (si#1, si#2 and si#3) successively." (PMID 34950036, 2021).
glioblastoma (1 paper, 2024). The most malignant astrocytic tumor (WHO grade IV). "In this study, we found that high expression of FBXO22 has stronger angiogenic and invasive ability and is associated with a worse prognosis, i.e., FBXO22 is able to promote glioblastoma malignant progression." (PMID 38519492, 2024). "Our study suggests that inhibiting FBXO22 expression is a potential intervention strategy for glioblastoma patients." (PMID 38519492, 2024). "Mechanistically, we revealed that FBXO22 stimulates the activation of the HIF-1α-VEGFA pathway by directly binding and mediating VHL ubiquitination degradation and promoting the malignant progression of glioblastoma." (PMID 38519492, 2024).
leukemia (1 paper, 2023). A malignant (clonal) hematologic disorder, involving hematopoietic stem cells and characterized by the presence of primitive or atypical myeloid or lymphoid cells in the bone marrow and the blood. "Giemsa-Wright staining displayed a lower frequency of immature blast cells in BM, together with less massive splenomegaly and significantly decreased leukemia infiltration in spleen and liver in secondary recipients of Fbxo22–/– AML cells." (PMID 36774506, 2023). "Consistent with the high expression of FBXO22 in human MLLr AML cells, we demonstrated that FBXO22 was also highly expressed in mouse GFP+ leukemia cells from a MLL-AF9-induced AML model, as determined by Western blot." (PMID 36774506, 2023). "In line, recipient mice receiving Fbxo22–/– leukemia cells showed remarkably prolonged survival times during secondary and tertiary transplantation." (PMID 36774506, 2023). "Upon FBXO22 knockdown, human MLLr leukemia cells presented markedly increased apoptosis." (PMID 36774506, 2023).
mesothelioma (1 paper, 2021). A usually malignant and aggressive neoplasm of the mesothelium which is often associated with exposure to asbestos. "Notably, the FBXO22 alterations in mesothelioma were all identified as “Amplification”." (PMID 35141150, 2021).
myeloid leukemia (1 paper, 2023). A clonal proliferation of myeloid cells and their precursors in the bone marrow, peripheral blood, and spleen. "In line, Fbxo22 deficiency significantly inhibited the engraftment of GFP+ myeloid leukemia cells in PB and BM of secondary recipient mice." (PMID 36774506, 2023).
pancreatic adenocarcinoma (1 paper, 2021). "Notably, FBXO22 methylation levels were also decreased in most tumors, and hypomethylation of FBXO22 was associated with poor overall survival, relapse-free interval, and progression-free interval in pancreatic adenocarcinoma." (PMID 35141150, 2021).
Parkinson disease (1 paper, 2022). A progressive degenerative disorder of the central nervous system characterized by loss of dopamine producing neurons in the substantia nigra and the presence of Lewy bodies in the substantia nigra and locus coeruleus. "GSE35642 database revealed that FBOX22 is upregulated in an animal model of Parkinson’s disease (PD) via the mechanism of promoting the ubiquitination-dependent degradation of PHLPP1 to ameliorate neurotoxicity, revealing the role of FBXO22 in PD occurrence and progression." (PMID 36425318, 2022).